PRKN (parkin RBR E3 ubiquitin protein ligase)
Description:
Functions within a multiprotein E3 ubiquitin ligase complex, catalyzing the covalent attachment of ubiquitin moieties onto substrate proteins. Substrates include SYT11 and VDAC1. Other substrates are BCL2, CCNE1, GPR37, RHOT1/MIRO1, MFN1, MFN2, STUB1, SNCAIP, SEPTIN5, TOMM20, USP30, ZNF746, MIRO1 and AIMP2. Mediates monoubiquitination as well as 'Lys-6', 'Lys-11', 'Lys-48'-linked and 'Lys-63'-linked polyubiquitination of substrates depending on the context. Participates in the removal and/or detoxification of abnormally folded or damaged protein by mediating 'Lys-63'-linked polyubiquitination of misfolded proteins such as PARK7: 'Lys-63'-linked polyubiquitinated misfolded proteins are then recognized by HDAC6, leading to their recruitment to aggresomes, followed by degradation. Mediates 'Lys-63'-linked polyubiquitination of a 22 kDa O-linked glycosylated isoform of SNCAIP, possibly playing a role in Lewy-body formation. Mediates monoubiquitination of BCL2, thereby acting as a positive regulator of autophagy. Protects against mitochondrial dysfunction during cellular stress, by acting downstream of PINK1 to coordinate mitochondrial quality control mechanisms that remove and replace dysfunctional mitochondrial components. Depending on the severity of mitochondrial damage and/or dysfunction, activity ranges from preventing apoptosis and stimulating mitochondrial biogenesis to regulating mitochondrial dynamics and eliminating severely damaged mitochondria via mitophagy. Activation and recruitment onto the outer membrane of damaged/dysfunctional mitochondria (OMM) requires PINK1-mediated phosphorylation of both PRKN and ubiquitin. After mitochondrial damage, functions with PINK1 to mediate the decision between mitophagy or preventing apoptosis by inducing either the poly- or monoubiquitination of VDAC1, respectively; polyubiquitination of VDAC1 promotes mitophagy, while monoubiquitination of VDAC1 decreases mitochondrial calcium influx which ultimately inhibits apoptosis. When cellular stress results in irreversible mitochondrial damage, promotes the autophagic degradation of dysfunctional depolarized mitochondria (mitophagy) by promoting the ubiquitination of mitochondrial proteins such as TOMM20, RHOT1/MIRO1, MFN1 and USP30. Preferentially assembles 'Lys-6'-, 'Lys-11'- and 'Lys-63'-linked polyubiquitin chains, leading to mitophagy. The PINK1-PRKN pathway also promotes fission of damaged mitochondria by PINK1-mediated phosphorylation which promotes the PRKN-dependent degradation of mitochondrial proteins involved in fission such as MFN2. This prevents the refusion of unhealthy mitochondria with the mitochondrial network or initiates mitochondrial fragmentation facilitating their later engulfment by autophagosomes. Regulates motility of damaged mitochondria via the ubiquitination and subsequent degradation of MIRO1 and MIRO2; in motor neurons, this likely inhibits mitochondrial intracellular anterograde transport along the axons which probably increases the chance of the mitochondria undergoing mitophagy in the soma. Involved in mitochondrial biogenesis via the 'Lys-48'-linked polyubiquitination of transcriptional repressor ZNF746/PARIS which leads to its subsequent proteasomal degradation and allows activation of the transcription factor PPARGC1A. Limits the production of reactive oxygen species (ROS). Regulates cyclin-E during neuronal apoptosis. In collaboration with CHPF isoform 2, may enhance cell viability and protect cells from oxidative stress. May protect neurons against alpha synuclein toxicity, proteasomal dysfunction, GPR37 accumulation, and kainate-induced excitotoxicity. May play a role in controlling neurotransmitter trafficking at the presynaptic terminal and in calcium-dependent exocytosis. May represent a tumor suppressor gene.
Synonyms: Parkin; PARK2; PDJ; AR-JP; LPRS2
Tractability: Small molecule: a structure with a bound ligand is known. PROTAC: UniProt records ubiquitination sites on it; ubiquitination databases record sites on it.
Gene: Protein-coding gene on chromosome 6 (161,347,417 to 162,727,775, reverse strand). Ensembl gene ENSG00000185345.
Subcellular location: Cytoplasm, cytosol; Nucleus; Endoplasmic reticulum; Mitochondrion; Mitochondrion outer membrane; Cell projection, neuron projection; Postsynaptic density; Presynapse
Subcellular location (Human Protein Atlas): Nuclear speckles; Cytosol
Pathways (Reactome):
Autophagy: Aggrephagy; PINK1-PRKN Mediated Mitophagy
Metabolism of proteins: Amyloid fiber formation; Josephin domain DUBs
Immune System: Antigen processing: Ubiquitination & Proteasome degradation
Programmed Cell Death: Regulation of necroptotic cell death
Gene Ontology:
Molecular function: actin binding; beta-catenin binding; cullin family protein binding; enzyme binding; F-box domain binding; G protein-coupled receptor binding; heat shock protein binding; histone deacetylase binding; Hsp70 protein binding; identical protein binding; kinase binding; PDZ domain binding; phospholipase binding; protein binding; protein kinase binding; protein-containing complex binding; protein-folding chaperone binding; transcription corepressor activity; tubulin binding; ubiquitin binding; ubiquitin conjugating enzyme binding; ubiquitin protein ligase activity; ubiquitin protein ligase binding; ubiquitin-protein transferase activity; ubiquitin-specific protease binding; and 2 more
Biological process: aggresome assembly; autophagy of mitochondrion; cellular response to toxic substance; free ubiquitin chain polymerization; host-mediated suppression of viral genome replication; mitochondrion to lysosome vesicle-mediated transport; mitophagy; negative regulation of actin filament bundle assembly; negative regulation of canonical Wnt signaling pathway; negative regulation of endoplasmic reticulum stress-induced intrinsic apoptotic signaling pathway; negative regulation of exosomal secretion; negative regulation of gene expression; negative regulation of glucokinase activity; negative regulation of insulin secretion; negative regulation of intralumenal vesicle formation; negative regulation of neuron apoptotic process; negative regulation of oxidative stress-induced neuron intrinsic apoptotic signaling pathway; negative regulation of reactive oxygen species metabolic process; negative regulation of release of cytochrome c from mitochondria; negative regulation of spontaneous neurotransmitter secretion; negative regulation of transcription by RNA polymerase II; positive regulation of canonical NF-kappaB signal transduction; positive regulation of gene expression; positive regulation of mitochondrial fusion; and 90 more
Cellular component: aggresome; cytoplasm; cytosol; endoplasmic reticulum; Golgi apparatus; mitochondrial outer membrane; mitochondrion; mitochondrion-derived vesicle; neuron projection; nuclear speck; nucleus; Parkin-FBXW7-Cul1 ubiquitin ligase complex; perinuclear region of cytoplasm; SCF ubiquitin ligase complex; ubiquitin ligase complex; Lewy body; postsynaptic density; presynapse; axon; dopaminergic synapse; endoplasmic reticulum membrane; glutamatergic synapse; Golgi membrane; intracellular vesicle; neuronal cell body; and 6 more
Genetic constraint (gnomAD): Loss-of-function variants: 47 observed, 51.23 expected, observed/expected ratio (o/e) 0.92, 90% interval 0.73 to 1.17. The upper end of that interval is the gene's LOEUF score, 1.17, which puts it in group 5 of 6, group 1 being the genes least tolerant of losing a copy. Missense variants: 612 observed, 583.85 expected, observed/expected ratio (o/e) 1.05, 90% interval 0.98 to 1.12. Synonymous variants: 241 observed, 221.57 expected, observed/expected ratio (o/e) 1.09, 90% interval 0.98 to 1.21.
Gene-disease validity (ClinGen):
ClinGen rates the evidence that PRKN causes each of these diseases.
Parkinson disease (autosomal recessive): Definitive. A progressive degenerative disorder of the central nervous system characterized by loss of dopamine producing neurons in the substantia nigra and the presence of Lewy bodies in the substantia nigra and locus coeruleus.
Homologues: Orthologues: chimpanzee PRKN (99% identical), macaque PRKN (97% identical), pig PRKN (86% identical), dog PRKN (85% identical), rat Prkn (85% identical), mouse Prkn (84% identical), guinea pig PRKN (81% identical), zebrafish prkn (60% identical), Drosophila melanogaster park (43% identical), Caenorhabditis elegans C17H11.6 (14% identical), Caenorhabditis elegans Y49F6B.9 (12% identical). Paralogues in human: ANKIB1 (18% identical), RNF14 (17% identical), RNF19A (17% identical), RNF19B (14% identical), ARIH1 (14% identical), ARIH2 (14% identical), RNF217 (13% identical), RNF144B (11% identical), RNF144A (11% identical).
Diseases named in the same sentence as PRKN in open-access papers:
PRKN is named in the same sentence as 260 diseases in open-access papers, as found by Europe PMC text mining. Sharing a sentence is not in itself a finding about the gene and the disease. The quoted sentences say what the papers report.
Parkinson disease (476 papers, 2007 to 2026). "Mutations in PRKN can disrupt these processes, contributing to the neurodegenerative changes observed in Parkinson's Disease." (PMID 41457744, 2026). "A 51‐year‐old Chinese man with 27‐year early‐onset Parkinson's disease harbored rare PRKN/PINK1 mutations." (PMID 40898742, 2025). "Mutations in the gene PRKN, which encodes the cytosolic E3 ubiquitin (Ub)-ligase parkin, are causative for early-onset Parkinson’s disease (PD)." (PMID 40827359, 2025). "Location of the breakpoints of all the PRKN structural variants identified in the two families and the sporadic Parkinson's disease case with short‐read whole genome sequencing, aligned on hg38." (PMID 40884420, 2025). "Mutations in PARK2 (also referred to as PRKN/PARKIN) lead to the second best‐known form of familial Parkinson's disease, accounting for nearly 50% of cases in its juvenile autosomal recessive form." (PMID 40734323, 2025). "In dopaminergic neurons derived from Parkinson’s disease patients with Parkin RBR E3 ubiquitin protein ligase (PRKN) loss-of-function mutations, the benzosulphonamide compound 39 effectively restored mitophagy to near-normal levels by inhibiting USP30." (PMID 40918504, 2025). "Mutations in the gene PRKN, many causative for different forms of early-onset Parkinson’s disease (PD), were discovered more than 25 years ago." (PMID 40827359, 2025). "The PINK1/PRKN pathway is closely associated with Parkinson’s disease and influences various cell processes in cancer cells." (PMID 39859167, 2025). "The second insight is that the PRKN gene, which is strongly associated with Parkinson’s disease, is a key player amongst the MD-associated genes." (PMID 40559334, 2025). "In cellular models of Parkinson’s disease with PRKN mutations, this compound restores mitophagy to near-normal levels while enhancing ubiquitination markers (TOM20, SYNJ2BP) and phosphoubiquitin accumulation." (PMID 40918504, 2025). "Clinical information of the affected Parkinson's disease cases with compound heterozygous PRKN structural variants." (PMID 40884420, 2025). "Due to the role of these proteins in DNA repair processes, loss of function of PRKN, a-Syn, and DJ-1 (Parkinsonism associated protein deglycase) has been linked to DNA damage in PD." (PMID 41300346, 2025). "Mutations in the autosomal dominant gene SNCA and the autosomal recessive gene PRKN can cause hereditary Parkinson’s disease." (PMID 40264664, 2025). "Complete loss of PINK1 or PRKN function unequivocally leads to death of dopamine (DA) neurons and early-onset Parkinson disease (PD), but the impact of reduced expression or activity on disease risk later in life is debated." (PMID 38041584, 2024). "The importance of the pathway is further underscored as complete loss of PINK1 or PRKN function are the most common causes of early-onset Parkinson’s disease (PD)." (PMID 40008113, 2024). "Our patient cohort included two rare monogenic cases of Parkinson's disease with homozygous mutations in the parkin gene (PRKN) or the G51D mutation in the alpha-synuclein gene (SNCA), respectively." (PMID 38059801, 2024). "PINK1 (PTEN induced kinase 1) and PRKN (parkin RBR E3 ubiquitin protein ligase) are the key players of this Ub-tagging process and complete loss of either enzyme leads to early-onset Parkinson disease (PD)." (PMID 38802071, 2024). "Individuals with either LRRK2 or biallelic PRKN variants were more likely to report a first-degree relative with Parkinson’s disease, likely attributed to higher penetrance of these gene variants." (PMID 39074992, 2024). "Dysregulation of pre-mRNA processing involving key ATG genes is linked to cancer progression, whereas splice mutations in genes such as PINK1 and PRKN are associated with Alzheimer’s and Parkinson’s diseases." (PMID 39537902, 2024). "The Parkinson’s disease duration was significantly greater among those with presumed compound heterozygous or homozygous PRKN variants." (PMID 39074992, 2024).
Parkinson disease (continued). "Loss-of-function mutations in the genes encoding PINK1 and PRKN result in early-onset Parkinson disease (EOPD)." (PMID 38293184, 2024). "The data presented here identify PRKN, a molecule known for its association with Parkinson’s Disease, as a mediator of antitumor immunity." (PMID 39213189, 2024). "Here, the authors apply deep mutational scanning to provide genotype-phenotype information for 99% of the possible PRKN variants and reveal mechanistic details on how some variants cause loss-of-function and Parkinsons disease." (PMID 38378758, 2024). "Patients with PRKN mutations on both alleles present with typical early-onset parkinsonism, including slow disease progression, positive levodopa responsiveness, absence of cognitive decline, resting tremor, rigidity, and levodopa-induced dyskinesia." (PMID 38732020, 2024). "Mutations in the PINK1 and PRKN genes are the most frequent genetic cause of early-onset Parkinson disease." (PMID 39329724, 2024). "If the gene encoding PRKN is mutated, it can lead to Parkinson's disease or autosomal recessive infant Parkinson's disease." (PMID 40226783, 2024). "We also identified a patient diagnosed with SCZ and early‐onset Parkinson's disease carrying biallelic pathogenic CNVs in PRKN." (PMID 37915257, 2024). "Complete loss-of-function mutations in the PRKN gene are a major cause of early-onset Parkinson’s disease (PD)." (PMID 38540783, 2024). "Defects in this pathway leading to the accumulation of damaged and dysfunctional mitochondria have been linked to neuronal toxicity in patients with Parkinson’s Disease (PD), where the PARK2 gene encoding PRKN can be mono- or biallelically altered." (PMID 39213189, 2024). "PRKN encodes Parkin, a component of the E3 ubiquitin ligase complex, and mutations in this gene have been implicated in Parkinson’s disease and Autism spectrum disorder." (PMID 37372391, 2023). "Dysfunctions in this process can be caused by mutations in genes like PRKN and are associated with the development and progression of Parkinson’s Disease (PD)." (PMID 37626726, 2023). "CNVs within the PRKN gene, either homozygous or compound heterozygous with sequence variants on the other allele, were a common cause of early-onset/familial Parkinson’s disease (n = 5)." (PMID 36781956, 2023). "We recently discovered that the expression of PRKN, a young-onset Parkinson disease-linked gene, confers redox homeostasis." (PMID 36691076, 2023). "In contrast, non-PRKN-linked parkinsonism cases revealed the same degree of carbonyl content as age-matched controls." (PMID 36691076, 2023). "PRKN, first found to be mutated in patients with early-onset Parkinson’s disease, has also been confirmed to carry mutations and deletions in human malignancies including glioblastoma, colon cancer, and lung cancers." (PMID 35832194, 2022). "Interest in the therapeutic potential of USP30 inhibitors has been driven by their application in Parkinson disease, for which some patients have loss of function mutations in the PRKN gene." (PMID 34844982, 2022). "This evidence raises the potential of GLP-1R agonists for treating both rare and more common neurological diseases with a strong mitochondrial component e.g. PRKN- or PINK1-associated Parkinson’s Disease." (PMID 35970890, 2022). "Deletions involving the PRKN gene are associated with Parkinson’s disease, autosomal recessive juvenile Parkinson’s disease (OMIM600116), and autism spectrum disorder." (PMID 36553064, 2022). "The overexpression of Parkin (PRKN), a mitophagy regulator that is associated with hereditary Parkinson’s disease, or PRKN-independent regulators reduced the release of mitochondria." (PMID 36551198, 2022). "We previously reported on two brothers who carry identical compound heterozygous PRKN mutations yet present with significantly different Parkinson’s Disease (PD) clinical phenotypes." (PMID 35768426, 2022).